LAG3 (lymphocyte activating 3)
Diseases named in the same sentence as LAG3 in open-access papers (continued):
Sharing a sentence is not in itself a finding about the gene and the disease.
tumor (continued). "Tumor-derived antigens induce LAG-3 overexpression and thereby lead to the depletion of CD8+ CTLs." (PMID 33329549, 2020). "Yet, the re-activation of T cells may remain insufficient to exert significant anti-tumor effect in vivo, suggesting alternate pathways of resistance including other inhibitory checkpoints, such as LAG3 and TIM3." (PMID 32331230, 2020). "Similarly, combining PD-1 blockade and the anti-LAG-3 antibody LBL-007 resulted in more effective control of tumor growth than the single agents alone." (PMID 33327433, 2020). "Co-blockade of LAG-3 and PD-1 could reverse T cell exhaustion and disrupt tumor growth more effectively than single antibody treatment, particularly for tumors that are resistant to singe antibody therapy." (PMID 32714324, 2020). "However, MHC-II molecules are ligands of LAG3, whose engagement on T cells is known to limit the T cell attack on tumor cells." (PMID 31703604, 2019). "Inhibitory tumor microenvironment binding inhibitory receptors, such as PD-1, CTLA-4, LAG-3, and TIM-3 on T cells might also cause insufficient response rates of CART cells in certain tumor entities, and therefore impair the immune attack." (PMID 31835562, 2019). "In this study, we determined 11 immunomodulators that are involved in tumor escape mechanisms and found 9 immunomodulators (LAG-3, TIM-3, CTLA-4, IFN-γ, ICOS, ICAM-1, TIGIT, NKG2A, and VISTA) that were upregulated in both high-immune score group and high-stromal score group." (PMID 31781309, 2019). "The association of LAG-3 and PD1 contributes to their rapid trafficking to the immunological synapse, leading to the synergistic inhibitory effect on T cell signaling in several tumor murine models." (PMID 32039024, 2019). "In view of its deregulated expression in tumor-infiltrating lymphocytes, LAG3, together with the additional immune checkpoint inhibitors CTLA4 and PD1, is considered a major target in order to reverse the immunosuppression typically mounting in oncologic diseases." (PMID 31623599, 2019). "The tumor microenvironment, with its persistent antigen exposure, leads to LAG3 overexpression." (PMID 31207938, 2019). "However, upon anti-PD-1 treatment, during post-partum mammary gland involution, the involution-initiated promotional effects on tumor growth are reversed and the PD-1, Lag-3 double positive population disappears." (PMID 31244852, 2019). "Therefore, blockade of LAG-3 is a mechanism which has the potential to improve tumor control via either a DC or T cell mediated mechanism." (PMID 30788290, 2019). "To investigate the potential checkpoint inhibitors in this PDA model, we examined the expression of programmed cell death protein 1 (PD-1), cytotoxic T-lymphocyte-associated protein 4 (CTLA-4), and lymphocyte-activation gene 3 (Lag-3) on T cells within the KPC tumor microenvironment." (PMID 30959852, 2019). "Indeed, the triple combination of domatinostat, anti-PD-1 and anti-LAG3 resulted in an increased response rate compared with the corresponding mono- or double therapies in the C38 tumor model." (PMID 31703604, 2019). "Alternatively, although Lag-3 is present on these tumor T cells, its actual capacity to repress their activation and function may be limited in comparison to that of CTLA-4 and PD-1." (PMID 31533840, 2019). "The expression of LAG-3in at least 1% (n = 25) of tumor-associated immune cells within the tumor margin was associated with an almost triple improvement in ORRs compared to patients without LAG-3 expression (n = 14) (20% and 7.1%, respectively)." (PMID 30991686, 2019).
tumor (continued). "Furthermore, compared to monotherapy, an anti-FGL1 mAb or anti-LAG-3 mAb in combination with an anti-B7-H1 mAb significantly reduces tumor burden and prolongs survival." (PMID 31681269, 2019). "LAG3 functions to control excessive activation following persistent antigen (Ag) exposure in an effort to prevent the onset of autoimmunity; however, it can also contribute to a state of T cell dysfunction in the tumor microenvironment (TME)." (PMID 31434339, 2019). "Similar to PD-1, LAG-3 is expressed on tumor-infiltrating lymphocytes (TILs), but to a less extent." (PMID 30863404, 2019). "A similar rationale applies to co-inhibitory receptors TIM-3 and LAG-3, in which blocking antibody-mediated anti-tumor efficacy might be compromised when the Fc maintains intact effector functions." (PMID 30863404, 2019). "LAG-3 is another important tumour immune checkpoint that may have synergistic effects with the PD-1/PD-L1 pathway." (PMID 30777100, 2019). "In addition, LAG-3 and PD-1 are co-expressed on tumor infiltrating lymphocytes (TIL)-specific CD8+ T cells in the peripheral blood and tumors of ovarian cancer patients resulting in T cell dysfunction." (PMID 32039024, 2019). "In particular, a recent study showed that the activation of LAG3 can resist the efficacy of anti-PD-1/B7-H1 therapy in tumor, and dual blockade of LAG3 and PD-1 can provoke more powerful antitumor or antiviral effects than the sum of blocking each molecule alone." (PMID 31440257, 2019). "Thus, LAG-3 blockade not only improves anti-tumor immune responses but also potentiates other forms of immunotherapy given its different mechanism of action mainly mediated by impeding cell cycle progression." (PMID 29544515, 2018). "The results also showed that the percentage of total CD8+ cells increased and the more severely exhausted PD1+CTLA-4+CD8+, PD1+Tim-3+CD8+, PD1+TIGIT+CD8+, and PD1+LAG-3+CD8+ T cells in the tumour infiltrating CD8+ T-cell population decreased after vvDD-IL-2-RG treatment." (PMID 30410056, 2018). "LSECtin exerts significant inhibitory function in anti-tumor immunity similar to LAG-3." (PMID 30603054, 2018). "Combination treatment of anti-SEMA4D with anti-LAG3 or epigenetic modulator entinostat resulted in maximal tumor growth delay and 90% CR (p<0.0001).Pepinemab treatment was well tolerated in a Phase I trial in patients with advanced refractory solid tumors (NCT01313065)." (PMID 30400822, 2018). "Besides, tumor-infiltrating Foxp3+LAG-3+Tregs secrete a higher level of immunosuppressive cytokines IL-10 and transforming growth factor-β (TGF-β) to collectively magnify Tregs activity." (PMID 30603054, 2018). "Recently, expression of LAG3 was found to be significantly higher on tumor-associated antigen (TAA)-specific CD8+ tumor-infiltrating T helper cells and CD8+ cytotoxic T cells in tumors than those in tumor-free liver tissues and blood of HCC patients." (PMID 29843754, 2018). "We and others have described expression of the ICRs PD-1, TIM-3, and LAG3 on various tumor-infiltrating immune cell types across tumor types, suggesting their targeting may have applicability for the treatment of multiple cancer types." (PMID 30400835, 2018). "Moreover, immunological assessment of the microenvironment in MMRD tumours exhibits enhanced attraction of tumour-infiltrating lymphocytes and widespread expression of several immune checkpoint ligands like PD-L1, LAG-3, IDO, and CTLA4." (PMID 30173350, 2018). "In a first phase (elimination phase), the stimulated immune system produced many costimulating cytokines (TNFα, IL1, IFNα, TLR, ICAM1, IL2, IL12, IFNγ,) and less inhibitors (IL10, IL4, IL13, PD1/PD-L1, prostaglandins, LAG-3, TGFβ) resulting in efficient tumor cell killing." (PMID 29492219, 2018). "Moreover, bindings of H3K9me3 and H3K27me3 were found to be reduced in the promoter loci of PD-1, CTLA-4, TIM-3, and LAG-3 in tumor tissues." (PMID 29983831, 2018).
tumor (continued). "Also, Tim-3 and LAG-3 transcripts were detected; expression of these exhaustion molecules was previously reported in tumor-reactive infiltrating lymphocytes following PD-1 immune checkpoint blockade (ICKB)." (PMID 29774030, 2018). "Because LAG-3 binding to MHC class II molecules activates myeloid cells, and MHC class II can be expressed by melanoma cells, engagement of LAG-3 with MHC class II might provide a survival signal to tumor cells." (PMID 30108594, 2018). "A recent study, which assesses the therapeutic effects of the CTLA-4 antibody ipilimumab, found ipilimumab might increase frequencies of tumor-infiltrating T cells expressing LAG-3 in metastatic melanoma patients." (PMID 30603054, 2018). "The sequencing and exact timing of LAG-3 and PD-1 blockade might be of particular relevance for the induction for optimal anti-tumor T cell responses." (PMID 29535740, 2018). "Herein, we shed light on the significance of LAG-3 in the tumor microenvironment, highlight its role to regulate different lymphocytes, interplay with other immune checkpoints especially PD-1, and emphasize new advances in LAG-3-targeted immunotherapy." (PMID 30603054, 2018). "Tumor regression correlated with presence and proliferation of PD1+Lag3+CD8+ T-cells in the tumor." (PMID 30400822, 2018). "Here we report the discovery of a novel LAG3 antibody, which showed a strong potency in the T cell activation and tumor growth inhibition in combination with anti-PD-L1 antibodies, indicating a potential therapeutic value of this antibody as a combination partner with PD-1 or PD-L1 agent." (PMID 30400822, 2018). "The levels of two pro-inflammatory cytokines, interferon gamma (IFN-γ) and tumor necrosis factor alpha (TNF-α), are significantly reduced in tumor microenvironments containing CD8+LAG-3+PD-1+ T-cells compared with those in the tumor milieu containing LAG-3+ or PD-1+CD8+ T-cells." (PMID 30271341, 2018). "For example, we found higher expression of Ctla4 and Lag3 in MLL-LNs that could inhibit anti-tumor immune responses." (PMID 29073272, 2017). "Additionally, Gal3 can inhibit CD8 positive cytotoxic T-cells in an LAG-3 dependent manner and thereby contribute to local immune tolerance and tumor promotion." (PMID 29284429, 2017). "Considering the potential role of MHC II on Tregs in mediating immune inhibition through LAG-3, interfering with the LAG-3/MHC class II pathway may help to prime or potentiate preexisting T cell responses to tumor antigens." (PMID 29225597, 2017). "Within the tumours of treated animals, CTLA-4 blockade gave rise to a significantly altered expression of markers associated with dysfunction (PD-1, Lag-3 and CD160), activation (CD25, GITR and CD38), as well as co-stimulation and development (CD27 and CD127) on mLama4-specific T cells." (PMID 28916749, 2017). "Blocks the binding of LAG3 to MHC-II thus decreasing tumor suppressive activity." (PMID 29387053, 2017). "Also various human cancer entities as well as tumor mouse models exhibit co-expression of PD-1 and LAG-3 on tumor-infiltrating T cells (TILs)." (PMID 28073373, 2017). "However, we also observed a trend towards delayed tumour growth following combinations of the vaccine with anti LAG-3 and PD-L1 therapy." (PMID 28537896, 2017). "HIF-1α-deficient tumor-infiltrating CD8+ lymphocytes were characterized by a drop in expression of the costimulatory molecules CD137 and GITR, and in the checkpoint receptors PD-1, LAG3, and TIM3." (PMID 29136509, 2017). "Moreover, treatment with anti-LAG-3/anti-PD-1 combination immunotherapy demonstrated higher efficacy in tumor eradication and the enhancement of adaptive immune responses as compared to monotherapy." (PMID 26700461, 2016).
tumor (continued). "While poxvirus-based immunotherapy resulted in PD-1mid CD8 T cells infiltrating into the tumor, we observed a moderate increase of LAG-3 expression in tumor infiltrating CD8 T cells following poxvirus-based immunotherapy alone, and an even greater increase following PD-1 blockade." (PMID 26910562, 2016). "However, we were able to employ two flow cytometry panels that included multiple T cell checkpoint molecules (PD-1, TIM-3, LAG-3) on anti-tumor T cell effector populations and immunosuppressive markers (PD-L1, PD-L2) on immunosuppressive myeloid subsets." (PMID 27539742, 2016). "We therefore postulated that patients may benefit from combining activation of tumor-specific effector T cells through poxvirus-based active immunotherapy with dual PD-1 and LAG-3 checkpoint inhibition." (PMID 26910562, 2016). "Antibody treatment with anti-CTLA-4 (p<0.02), anti-BTLA (p<0.01), anti- PD-L1 (p<0.01), anti- Lag-3 (p<0.001) and anti- PD-1 antibodies (p<0.02) led to a modest but a significant delay in tumor growth in MC-38 bearing mice (p values compared to mice that received isotype control antibody)." (PMID 27050669, 2016). "Lastly, dual blockade of PD-1 and LAG-3 inhibited the tumor growth of SCCs." (PMID 27835902, 2016). "Notably, when MVA-BN-HER2 immunotherapy was combined with dual PD-1 and LAG-3 immune checkpoint blockade in subsequent experiments, complete tumor regression was observed in all mice." (PMID 26910562, 2016). "Speculatively, this could be a mechanism of immune evasion by tumor cells and warrants further studies elucidating the prevalence of LAG-3 expression in prostate tissue of PC patients." (PMID 26993768, 2016). "Indeed, preclinical data have shown that in vivo co-inhibition or knock-out of LAG-3 and PD-1 demonstrated robust immune activation, tumor rejection, and abrogation of self-tolerance." (PMID 26850630, 2016). "Expression of LAG-3 and PD-1 was up-regulated by IL-10, IL-6 and tumor-derived APCs." (PMID 26700461, 2016). "In addition, the combination of anti-CTLA4, anti-TIM-3 and anti-LAG-3 produced further suppression of B16F10 tumor growth." (PMID 25614821, 2015). "Blocking LAG-3 could thus help the body fight tumor cells on two fronts, and blocking PD-1 in conjunction, which also promotes immuno-tolerance of tumor antigens, might have a synergistic effect." (PMID 29546098, 2015). "However, we also noted that some T-cells infiltrating the tumor exhibited the phenotype of exhausted T-cells (CTLA4+/LAG3+/TIM3+/IDO+)." (PMID 25940795, 2015). "Specifically, OX40 agonists induce expansion and infiltration of effector T cells into the tumor, and the cytotoxic activity of these cells in the tumor microenvironment may be supported by LAG3 blockade." (PMID 25763356, 2015). "Notably, the frequencies of IFN-γ-producing tumor-reactive CD8 T cells from anti-PD-L1/CTLA4 treated mice were similar to those treated with the anti-PD-L1/LAG-3 and anti-PD-L1/TIM-3 combinations." (PMID 25614821, 2015). "It is possible that anti-tumor synergy produced by anti-PD-L1 in combination with anti-LAG-3 or anti-TIM-3 antibodies may be a less toxic alternative to anti-PD-L1 in combination with anti-CTLA4 antibodies." (PMID 25614821, 2015). "Additionally, another in vivo study, applying a dual anti-LAG-3/anti-PD-1 antibody therapy showed a markedly improvement of the overall condition of mice challenged with tumor, that were resistant to single antibody treatment." (PMID 24348481, 2013). "Also, antibody blockade of LAG-3 in two murine models of self- and tumor-tolerance increased the accumulation and effector function of antigen-specific CD8+ T cells." (PMID 22190971, 2011). "Therefore, combined blockade of LAG-3 and PD-1 might more efficiently overcome T-cell exhaustion mechanisms and restore effector functions, leading to tumor regressions." (PMID 40234667, 2025).
tumor (continued). "The downregulation of MHC class II expression on tumor cells after anti-PD-1 therapy in this study may contribute to resistance to anti-PD-1 therapy because it evades LAG-3 axis-mediated immunosuppression but inhibits activation of antitumor immune responses mediated by CD4-positive T cells." (PMID 40801643, 2025). "It maintains immune system homeostasis under normal physiological conditions, while LAG-3 and Treg cell interactions stimulate Treg activity, strengthen immune tolerance, and indirectly suppress dendritic cell (DC) function, thereby facilitating tumor cell immune escape." (PMID 40438098, 2025). "Moreover, it was found that LAG‐3 was upregulated after anti‐PD‐L1 therapy resistance, thereby introducing a new way to monitor efficacy markers and immunotherapy resistance as well as overcome the challenges posed by tumor heterogeneity." (PMID 39513410, 2025). "The manufactured CAR-T cells express low levels of exhaustion or inhibitory checkpoint molecules like PD-1, TIM-3, and LAG-3 confirming less susceptibility for inhibitory signals from tumor cells and validating their non-exhausted and high functional phenotype." (PMID 40248244, 2025). "However, the impact of LAG3 on prognosis varies across different tumor types." (PMID 40411616, 2025). "Additionally, alterations in the tumor immune microenvironment may offer valuable insights for subsequent combination immunotherapies, such as PD‐1/L1 inhibitors and LAG3 inhibitors." (PMID 40492508, 2025). "Given the substantially improved anti-tumour immune responses and anti-Lag3 efficacy following CX-5461 treatment, dual blockading of ribosome biogenesis and LAG3 may be efficacious in immunotherapeutic-resistance cases and is considered a beneficial therapeutic approach." (PMID 40646287, 2025). "We speculate that LAG3 may regulate inflammatory vesicle activation via IL‐1β feedback, a pathway that warrants further investigation in the future given the dual role of IL‐1β in tumor promotion and suppression." (PMID 41025546, 2025). "In addition to PD-1, PD-L1, and CTLA-4, other inhibitory receptors—including T cell immunoglobulin and mucin-domain containing-3 (TIM-3) and lymphocyte activation gene-3 (LAG-3)—are increasingly recognized as markers and mediators of T-cell dysfunction within the tumor microenvironment." (PMID 40943541, 2025). "Additionally, early-stage clinical data suggest improved anti-tumour response in MSS CRC patients treated with favezelimab (anti-LAG-3) plus pembrolizumab (anti-PD-1), versus pembrolizumab monotherapy (objective response rate [ORR] 6.3% [n = 5/80] versus 0% [n = 0/20], respectively)." (PMID 40016550, 2025). "Our findings provide insights into the safety profile of combined PD-1 and LAG-3 blockade in gastroesophageal cancer and highlight the potential of ctDNA analysis to dynamically assess systemic tumor burden during neoadjuvant ICI that may open a therapeutic window for future intervention." (PMID 38504015, 2024). "Moreover, when CAR T cells lose their functionality, they may express immune checkpoint molecules such as PD-1, TIM-3, and LAG-3, which may further impede their anti-tumor activity." (PMID 38683232, 2024). "Therefore, the role of YY1 in tumor immune resistance may be related to the overexpression of PD-L1 on cancer cells and plausibly LAG-3 on CD8 T cells." (PMID 39796650, 2024). "Furthermore, LAG3 has been found to be expressed on tumor‐infiltrating CD4+ and CD8+ T cells." (PMID 39565059, 2024).